DPP4 (dipeptidyl peptidase 4)
Diseases named in the same sentence as DPP4 in open-access papers (continued):
Sharing a sentence is not in itself a finding about the gene and the disease.
type 2 diabetes (continued). "Type 2 diabetes treatments targeting the GLP-1 axis by either inhibiting its clearance by DPP4 or using GLP-1 mimetics are currently used." (PMID 26488296, 2015). "We performed a systematic review and meta-analysis of head-to-head studies to compare GLP-1 analogues with DPP-4 inhibitors in the management of type 2 diabetes." (PMID 25089625, 2014). "Even newer anti diabetic medication as the dipeptidyl peptidase-4 inhibitor Saxagliptin has been shown to improve the function of circulating pro-angiogenic cells from type 2 diabetic patients." (PMID 25300286, 2014). "DPP-4 inhibitor as a third-line add-on therapy can achieve significant glycaemic improvement in patients with type 2 diabetes inadequately controlled on the combination of metformin and sulphonylurea." (PMID 25180036, 2014). "The purpose of the present study is, therefore, to examine the efficacy of DPP-4 inhibitors when given as add-on therapy to the combination of metformin and sulphonylurea in patients with type 2 diabetes and suboptimal glycaemic control." (PMID 25180036, 2014). "DPP-4 inhibitor therapy in patients with type 2 diabetes was shown to increase circulating SDF-1α and EPC levels." (PMID 25140306, 2014). "Dipeptidyl peptidase (DPP)-4 inhibitors have emerged as a new category of oral hypoglycemic agents for type 2 diabetes, which are widely used worldwide." (PMID 24578754, 2014). "Sitagliptin, an oral dipeptidyl-peptidase-4 (DPP-4) inhibitor, was approved in the United States in 2006 for the treatment of type 2 diabetes." (PMID 24817885, 2014). "Sitagliptin is a selective DPP-4 inhibitor and it was approved for the treatment of type 2 diabetes mellitus (T2DM) at the end of 2009 in Japan." (PMID 27419209, 2014). "The impact of a DPP-4 inhibitor on endothelial dysfunction in patients with type 2 diabetes is controversial." (PMID 25074318, 2014). "It has also been found in clinical studies that inhibition of DPP-4 leads to a decrease of the elevated postprandial levels of TGs, CMs and apoB48 in patients with type 2 diabetes." (PMID 25110536, 2014). "Inhibition of DPP-4 leads to a decrease of the elevated postprandial levels of TGs, CMs and apoB48 in patients with type 2 diabetes." (PMID 25110536, 2014). "Many studies have shown that treatment with DPP-4 inhibitor improves endothelial function in patients with type 2 diabetes, in both GLP-1-dependent and -independent manners." (PMID 25140306, 2014). "Comparative evaluation of the effects of different DPP-4 inhibitors on lipid metabolism will be required in the future to determine the best agent for lipid control in patients with type 2 diabetes and hyperlipidemia." (PMID 25110536, 2014). "As type 2 diabetes is becoming more common in Asia with the progressive increase in affluence of this region, it is important to determine if the better response to DPP-4 inhibitors in Asian patients can be confirmed." (PMID 25180036, 2014). "This study suggested the usefulness of DPP4 inhibitors in Japanese patients with type 2 diabetes, and also reinforces the importance of low-dose SU for effective glycemic management." (PMID 24578754, 2014). "Before the use of DPP-4 inhibitors for the treatment of type 2 diabetes, DPP-4 had been intensively studied as an immune regulator because it acts as a T cell costimulator and a binding partner of adenosine deaminase (ADA)." (PMID 25140306, 2014). "This study indicated the usefulness of dipeptidyl peptidase (DPP)-4 inhibitors in Japanese patients with type 2 diabetes, and also reinforces the importance of low doses of sulfonylurea for effective glycemic management." (PMID 24578754, 2014). "Dipeptidylpeptidase 4 (DPP-4) inhibitors are a new class of blood glucose-lowering drug, have been approved for treatment of type 2 diabetes, and take the advantage of having low risk of hypoglycemia and neutral effect on body weight." (PMID 25471116, 2014).
type 2 diabetes (continued). "Recent clinical studies have reported that DPP-4 inhibitors such as vildagliptin and sitagliptin improve postprandial atherogenic TG-rich lipoprotein levels in patients with type 2 diabetes." (PMID 23298374, 2013). "Although these reports suggest efficacy and safety of DPP-4 inhibitors for the treatment of patients with type 2 diabetes undergoing HD, caution should still be exercised when treating patients undergoing HD." (PMID 23445717, 2013). "Since DPP4 is known to inactivate incretin hormones involved in glucose-dependent insulin secretion, pharmacological DPP4-inhibitors have been developed to improve the treatment of type 2 diabetes." (PMID 23379505, 2013). "DPP-4 inhibitors (DPP-4is) have protective effects against type-2 diabetes and several metabolic disorders." (PMID 23696840, 2013). "Alogliptin is a selective dipeptidyl peptidase IV (DPP-4) inhibitor and a member of a new class of oral medications, which includes sitagliptin, vildagliptin, saxagliptin, linagliptin, for the treatment of type 2 diabetes." (PMID 23762423, 2013). "Incretin-based therapies such as GLP-1 receptor agonists and DPP-4 inhibitors are currently in use for the management of type 2 diabetes." (PMID 23450079, 2013). "Glucagon-like peptide-1 (GLP-1) receptor agonists and dipeptidyl peptidase 4 (DPP4) inhibitors are currently used as glucose-lowering agents in type 2 diabetes, due to their effects on insulin and glucagon secretion." (PMID 23853775, 2013). "Several studies have shown the effectiveness of sitagliptin, a dipeptidyl peptidase-4 inhibitor, for type 2 diabetes, with a hypoglycemic effect being demonstrated both when it is administered alone or in combination with other oral antidiabetic agents." (PMID 23671547, 2013). "In recent years, medications that mimic or enhance incretin activity, such as glucagon-like peptide (GLP)-1 receptor agonists and dipeptidyl peptidase (DPP)-4 inhibitors, have emerged as important new treatments for type 2 diabetes." (PMID 23445717, 2013). "We know that chronic hyperglycaemia induces a significant increase in DPP4 activity in type 1 and type 2 diabetes." (PMID 23853775, 2013). "Since GLP-1 and GIP augment glucose-induced insulin release from pancreatic b-cells, suppresses glucagon secretion, and slows gastric emptying, inhibition of DPP-4 has been proposed as a potential therapeutic target for the treatment of type 2 diabetes." (PMID 23984879, 2013). "Sitagliptin is a dipeptidyl peptidase-4 inhibitor that is used to treat diabetes, especially patients with type 2 diabetes and reduced incretin activity." (PMID 23671547, 2013). "GLP-1 receptor agonists (incretin or GLP-1 mimetics) and dipeptidyl peptidase-4 (DPP-4) inhibitors (CD26 antigen inhibitors) are the currently available incretin-based therapies proven to be safe and effective in the management of type 2 diabetes." (PMID 23450079, 2013). "Dipeptidyl peptidase 4 (DPP4) is involved in the regulation of incretins GLP-1 and GIP that control blood sugar, and DPP4 inhibitors Sitagliptin, Vildagliptin and Saxagliptin are approved as drugs to treat type 2 diabetes." (PMID 24265767, 2013). "Linagliptin is a highly specific and potent inhibitor of DPP-4 that is currently indicated for the treatment of type 2 diabetes." (PMID 23697612, 2013). "Among the DPP-4 inhibitors, alogliptin is still under investigation for treatment of type 2 diabetes as monotherapy or in combination with other antidiabetic drugs." (PMID 23452780, 2013). "Alogliptin is a new dipeptidyl peptidase (DPP-4) inhibitor, which is under investigation for treatment of type 2 diabetes either alone or in combination with other antidiabetic drugs." (PMID 23452780, 2013). "In patients with type 2 diabetes, DPP-4 inhibition leads to higher levels of active incretins, both during fasting and post meal, which in turn lead to higher insulin release, lower glucagon levels, and improved fasting and post meal glucose concentrations." (PMID 23554750, 2012).
type 2 diabetes (continued). "Several orally active DPP-4 inhibitors have now been developed to treat type 2 diabetes, including sitagliptin, vildagliptin and saxagliptin, and sitagliptin was approved in the United States in October, 2006 for the treatment of patients with type 2 diabetes." (PMID 23554750, 2012). "Dipeptidyl peptidase-4 (DPP-4) inhibitors are the most recently approved class of agent for Type 2 diabetes therapy." (PMID 24300302, 2012). "Sitagliptin is a DPP-4 inhibitor, which is believed to exert its actions in patients with type 2 diabetes by slowing the inactivation of incretin hormones." (PMID 23554750, 2012). "We plan to prospectively investigate the effects of dipeptidyl peptidase-4 inhibition with vildagliptin on a number of atherothrombotic markers and adipokines in patients with proven atherosclerosis and type 2 diabetes." (PMID 22672501, 2012). "The aim of this study was to compare the efficacy and safety of once-daily human glucagon-like peptide-1 analogue liraglutide with dipeptidyl peptidase-4 inhibitor sitagliptin, each added to metformin, over 52 weeks in individuals with type 2 diabetes." (PMID 21355967, 2011). "Sitagliptin is a dipeptidyl peptidase-4 (DPP IV, CD26) inhibitor indicated for treatment of Type II diabetes as a second line therapy after metformin." (PMID 20462426, 2010). "Another (non-S28 family) dipeptidyl dipeptidase (DPP4) is a major drug target in type 2 diabetes, and Merck has already developed a successful inhibitor of DPP4, the anti-hyperglycemic drug sitagliptin, for the treatment of type 2 diabetes." (PMID 20598110, 2010). "Sitagliptin is an oral, once-daily and highly selective dipeptidyl peptidase-4 (DPP-4) inhibitor for the treatment of patients with type 2 diabetes." (PMID 18954434, 2008). "Sitagliptin, a highly selective dipeptidyl peptidase-4 inhibitor, is the first in a new class of oral antihyperglycemic agents (AHAs) for the treatment of patients with type 2 diabetes." (PMID 18954434, 2008). "Exendin 4 and inhibitors of dipeptidyl peptidase 4 (DPP-4 inhibits GLP-1 breakdown) are new drugs already approved for use as adjuvant therapy in Type 2 diabetes." (PMID 19046214, 2008). "We compared 1:1 propensity score-matched patients with type 2 diabetes newly initiating SGLT2 inhibitors versus dipeptidyl peptidase-4 (DPP4) inhibitors (n = 718,798), GLP-1 RAs versus DPP4 inhibitors (n = 623,390), and SGLT2 inhibitors versus GLP-1 RAs (n = 702,808) from 2016 to 2024." (PMID 41790761, 2026). "Sitagliptin is a dipeptidyl peptidase-4 (DPP-4) inhibitor used to treat type 2 diabetes." (PMID 42075935, 2026). "In this large real-world cohort of individuals with type 2 diabetes and bipolar disorder, initiation of SGLT-2 inhibitor therapy was associated with a significantly lower risk of suicide-related events compared to initiation of a DPP-4 inhibitor." (PMID 40567368, 2025). "Consequently, as the only approved bi-weekly DPP-4 inhibitor, cofrogliptin is well-positioned to substantially improve medication adherence among patients with type 2 diabetes, thereby improving therapeutic outcomes." (PMID 41560728, 2025). "Inhibition of DPP‐4 activity specifically results in higher glucagon‐like peptide‐1 levels, and increases the half‐life of circulating insulin, thereby enhancing glycemic control in individuals with type 2 diabetes." (PMID 40905017, 2025). "Dipeptidyl peptidase-4 (DPP-4) inhibitors, approved for type 2 diabetes, enhance endogenous incretin action and may enhance β-cell function." (PMID 41026724, 2025). "Sitagliptin is a reversible DPP4 inhibitor often used in the treatment of type 2 diabetes." (PMID 40780446, 2025). "Consequently, DPP-4 inhibition promotes insulin secretion and prevents the onset of type 2 diabetes." (PMID 41517158, 2025). "DPP-4 inhibitors, commonly used to treat type II diabetes, could be repurposed as anticancer agents to effectively modulate immune responses." (PMID 40565099, 2025).
type 2 diabetes (continued). "The present study aims to investigate comparative dementia risk with initiators of GLP1 receptor agonists, SGLT2 inhibitors, or DPP4 inhibitors in people with type 2 diabetes aged ≥ 60 years, using real-world observational data from primary care practice records in the UK." (PMID 41420258, 2025). "Beyond its established glucose-lowering effects, metformin has also been shown to enhance GLP-1 secretion, potentially by delaying carbohydrate absorption and modulating DPP-4 activity, contributing to improved incretin responses in patients with type 2 diabetes." (PMID 40904779, 2025). "DPP4-inhibitors are glucose-lowering drugs frequently prescribed for type 2 diabetes." (PMID 41141478, 2025). "Some studies report an inverse correlation between IBD activity and serum DPP-4 levels, while others suggest that long-term DPP-4 inhibitor use in patients with type 2 diabetes may increase IBD risk." (PMID 40723884, 2025). "DPP4 inhibitors, also known as “gliptins”, have been added to treatment regimens of type 2 diabetes, as they strongly reduce DPP4-mediated inactivation of the incretin hormones glucagon like peptide-1 (GLP-1) and gastric inhibitory polypeptide (GIP) and thus lower blood glucose levels." (PMID 40817204, 2025). "A variety of DPP-4 inhibitors are available, differing in dosing frequency, metabolism, and excretion pathways, allowing for individualized selection based on renal function, liver function, and lifestyle considerations in individuals with type 2 diabetes." (PMID 40607140, 2025). "We aim to investigate comparative dementia risk associated with glucagon-like peptide-1 receptor agonists (GLP1-RAs), sodium-glucose cotransporter-2 inhibitors (SGLT2i), and dipeptidyl peptidase-4 inhibitors (DPP4i) in adults aged ≥ 60 years with type 2 diabetes." (PMID 41420258, 2025). "Among patients aged 65 years or older with type 2 diabetes, DPP-4 inhibitors were associated with a lower mortality rate, fewer MACE, and no increase in HF or hypoglycemia, which supports the concept that elderly individuals benefit from DPP-4 inhibitors." (PMID 40771927, 2025). "DPP4 inhibitors are a class of hypoglycemic drugs used in type 2 diabetes." (PMID 38762508, 2024). "We conducted a 26-week, randomized, open-label, parallel-group study, including a 1-2 week drug washout period, in patients with type 2 diabetes with HbA1c ≥7.0% and <9.0% and BMI ≥20 kg/m2 despite treatment with a drug naïve or other than DPP-4 inhibitors or SGLT2 inhibitors." (PMID 39497800, 2024). "Genetic variants associated with glycated hemoglobin (HbA1c), Type 2 Diabetes (T2D), and antidiabetic drug targets (KCNJ11, ABCC8, PPARG, INSR, GLP1R, SLC5A2, and DPP4) were sourced from genome-wide association studies in the UK Biobank and the DIAMANTE consortium." (PMID 39640975, 2024). "DPP-4 inhibitors may be considered as the first-line treatment for individuals with type 2 diabetes when biguanides are difficult to use or when insulin secretion is impaired." (PMID 38256615, 2024). "Currently, there are several classes of orally administered pharmacological agents available for the therapy of type 2 diabetes, such as sulfonylureas, metformin, dipeptidyl peptidase IV (DPP-4) inhibitors and oral glucagon-like peptide 1 (GLP-1) receptor agonists." (PMID 38503901, 2024). "The shedding of DPP-4 from the cell surface increases in high glucose conditions, which may contribute to the increased circulating DPP-4 observed in patients with type 2 diabetes." (PMID 38476668, 2024). "This study aimed to evaluate the association between DPP-4 inhibitor use and cognitive functions, serum brain-derived neurotrophic factor (BDNF), and pentraxin-3 (PTX-3) levels in patients with type 2 diabetes, compared with the patients who only use metformin treatment." (PMID 38510866, 2024). "However, dipeptidyl peptidase-4 (DPP-4) inhibitors, alongside biguanides, are increasingly used as the first-line therapy for type 2 diabetes (T2DM) in Japan." (PMID 39121166, 2024).
type 2 diabetes (continued). "DPP-4 inhibitors are therefore often used to treat people with type 2 diabetes." (PMID 38337597, 2024). "Treatment with the iSGLT2 dapagliflozin reduced DPP4 serum levels in patients with type 2 diabetes and non-alcoholic fatty liver disease, while the DPP4 inhibitor sitagliptin ameliorated the ischemia/reperfusion-induced injury in cardiomyocytes by mediating SIRT3 upregulation and autophagy." (PMID 38811901, 2024). "Researchers have emphasized the potential of peptides derived from food proteins as natural DPP4 inhibitors that may have complementary or additive effects in managing type 2 diabetes." (PMID 38004494, 2023). "DPP4 inhibitors are a class of medications that are used to treat type 2 diabetes." (PMID 37896834, 2023). "Previous CVOTs have not shown that DPP-4 inhibitors have any significant prognostic superiority over placebo in people with type 2 diabetes and a history of CVD or a high risk of CVD2–5." (PMID 37669959, 2023). "DPP4 rapidly converts glucagon-like peptide-1 (GLP-1) and glucose-dependent insulinotropic peptide (GIP) into an inactive form, causing a deficiency in insulin secretion commonly found in type 2 diabetes patients." (PMID 38004494, 2023). "MK3102 is a potent DPP4 inhibitor for type-2 diabetes patients." (PMID 37658227, 2023). "DPP4 inhibitors have been widely used as therapeutic agents for type 2 diabetes." (PMID 37350750, 2023). "This cohort study assesses the risk of fractures associated with sodium-glucose cotransporter 2 inhibitors vs incretin-based drugs of dipeptidyl-peptidase 4 inhibitors and glucagon-like peptide 1 receptor agonists, separately, in postmenopausal individuals with type 2 diabetes." (PMID 37751205, 2023). "Therefore, the choice of treatment with DPP-4 inhibitors in the elderly patient with type 2 diabetes should take into account of comorbidities, especially heart failure." (PMID 36964858, 2023). "DPP-4 inhibitors are a group of antihyperglycemic medications used to manage type-2 diabetes." (PMID 38162307, 2023). "This study compared risk of cardiovascular events in patients within routine care settings in Europe and Asia with type 2 diabetes (T2D) initiating empagliflozin compared to dipeptidyl peptidase-4 inhibitors (DPP-4i) stratified by pre-existing CVD and history of heart failure (HF)." (PMID 37653496, 2023). "For example, some of the anti-diabetic drugs such as biguanides, SGLT2 inhibitors, DPP-4 inhibitors, sulfonylureas, and insulin, which have been commonly administered for the management of type-2 diabetes, are reported to exacerbate the clinical conditions in COVID-19." (PMID 36839456, 2023). "DPP4 is an exopeptidase that selectively cleaves N-terminal dipeptides from a variety of substrates and is best known for cleaving and inactivating glucagon-like peptide-1 (GLP-1) to disrupt glucose homeostasis associated with type 2 diabetes." (PMID 37097759, 2023). "Here, we explored whether gemigliptin, a dipeptidyl peptidase 4 (DPP4) inhibitor for treatment of type 2 diabetes, can induce autophagy and regulate inflammasome activation as a potential NASH treatment independent of its anti-diabetic effect." (PMID 37739179, 2023). "Cho used lecithin nano-liposome particle as a CRISPR/Cas9 complex delivery system for treating type 2 diabetes by downregulating the expression of enzyme dipeptidyl peptidase-4 (DPP-4) gene, which can block the degradation of glucagon-like peptide-1 (GLP-1) by DDT-4." (PMID 37163428, 2023). "This study aimed to compare glycemic control and the incidence of hypoglycemia and chronic complications among adult patients with type 2 diabetes prescribed metformin, dipeptidyl peptidase-4 inhibitors (DPP4I), and sulfonylurea (SU) as monotherapy or dual combination therapy." (PMID 35212277, 2022). "In addition, the combination results in higher bone protective incretin levels such as GLP-1 in type-2 diabetes patients as compared to the DPP-4 inhibitor alone." (PMID 35928902, 2022).